ATXN3 (ataxin 3)
Diseases named in the same sentence as ATXN3 in open-access papers (continued):
Sharing a sentence is not in itself a finding about the gene and the disease.
cancer (continued). "Nevertheless, there is emerging evidence indicating that Ataxin-3, Ataxin-3L, JOSD1, and JOSD2 are also implicated in cancer progression." (PMID 32982735, 2020). "Furthermore, in breast cancer, ATXN3 promotes metastasis by deubiquitinating KLF4, a transcription factor frequently overexpressed in various human cancers and closely associated with tumorigenesis and tumor progression." (PMID 38815863, 2024). "Ataxin-3 is the principal pathogenic protein in MJD and also appears to be involved in cancer." (PMID 38497605, 2024). "Since both HIF-1α and HIF-2α have been identified as PD-L1 transcription factors in cancer cells in response to hypoxia, we then reasoned whether ATXN3 enhances tumoral PD-L1 transcription through stabilizing HIF family transcription factors." (PMID 38038129, 2023). "Nevertheless, our CRISPR screening identified ATXN3 as a previously unknown positive regulator in cancer cells." (PMID 38038129, 2023). "ATXN3 promotes PD-L1 expression at transcriptional level in a broad spectrum of cancer cells." (PMID 38038129, 2023). "Positive correlation of ATXN3 with PD-L1 levels in human cancers." (PMID 38038129, 2023). "Interestingly, ataxin-3 is suggested to be responsible for repressing PTEN transcription in cancer which further emphasizes the importance of the AKT signaling pathway in disease progression." (PMID 33741019, 2021). "Thus, ATXN3 provides an autonomous, complementary therapeutic target in cancers with epigenetic downregulation of PTEN." (PMID 24292675, 2014). "Our study further reveals that ATXN3 exerts its tumor-suppressive functions by safeguarding Galectin-9, a carbohydrate-binding protein known for inducing apoptosis and inhibiting the proliferation of human cancer cells, from ubiquitination-mediated proteasomal degradation." (PMID 38815863, 2024). "In addition, ATXN3 has been demonstrated to play a role in maintaining genome stability, raising a possibility that targeted suppression of ATXN3 enhances clonal neoantigens in cancer cells." (PMID 38038129, 2023). "Importantly, analysis of the TCGA database showed a statistically significant positive correlation between ATXN3 and PD-L1 expression in the majority of types of human cancers, implying that ATXN3 is a positive regulator of PD-L1 in a broad spectrum of human cancers." (PMID 38038129, 2023). "Importantly, coexpression of IRF1 and STAT3 in ATXN3-KO cancer cells fully rescued IFN-γ–induced PD-L1 expression, but had little effect on hypoxia-induced PD-L1 expression, confirming that ATXN3 promotes IFN-γ–induced PD-L1 expression specifically through stabilizing IRF1 and STAT3." (PMID 38038129, 2023). "Therefore, our data support ATXN3 regulation of PD-L1 signaling in human cancer." (PMID 38038129, 2023). "However, the possibility that targeting ATXN3 in non-cancer cells may alter immune functions as a result of accelerated STAT3, IRF1, and HIF-2α degradation cannot be excluded." (PMID 38038129, 2023). "Second, analysis of the TCGA database revealed a statistically significant positive correlation between ATXN3 and CD274 expression in most types of human cancers." (PMID 38038129, 2023). "TCGA database analysis revealed a positive correlation between ATXN3 and CD274 in more than 80% of human cancers." (PMID 38038129, 2023). "Consequently, overexpression of ATXN3 dramatically increased JunB protein expression and prolonged JunB half-life, indicating that JunB stabilization by ATXN3 may be involved in PD-L1 upregulation in cancer cells." (PMID 38038129, 2023). "In these cells, TSPAN8 enhances Sonic Hedgehog (SHH) signaling, stabilizes the expression of protein patched homolog 1 (PTCH1) by recruiting ataxin-3 (ATXN3), and promotes cancer stemness." (PMID 32138170, 2020).
cancer (continued). "HIF-1α expression was elevated in cancer tissues versus non-cancerous tissues, with hypoxic conditions differentially regulating ATXN3 via HIF-1α across cell lines." (PMID 41507147, 2026). "Therefore, Ataxin-3 presents as an independent and complementary therapy target with downregulation expression of PTEN in cancers." (PMID 32982735, 2020). "Interestingly, ATXN3 appears to positively regulate PD-L1 expression at the transcriptional level, since real-time reverse transcription PCR analysis confirmed that Atxn3 targeting dramatically inhibited Cd274 mRNA expression in both LLC1 and B16 mouse cancer cells." (PMID 38038129, 2023). "However, HIF-2α expression could not rescue ATXN3-KO cancer cell expression of PD-L1 under hypoxia conditions, nor by IFN-γ stimulation, suggesting that additional genes are involved in the ATXN3/HIF-2α pathway to control hypoxia-induced PD-L1 expression." (PMID 38038129, 2023). "Depletion of ATXN3 was sufficient to attenuate Akt phosphorylation and enhance the ability of histone deacetylase inhibitors (HDACi) to induce PTEN expression and decrease cell viability, suggesting ATXN3 inhibition may be of therapeutic benefit in cancers with nongenetic inactivation of PTEN." (PMID 24292675, 2014). "Interestingly, co-IP and Western blot analysis detected the interaction of JunB, but not c-Jun, with ATXN3 in transiently transfected HEK293T cells, implying a possibility that ATXN3 may enhance AP-1–mediated PD-L1 gene transcription in cancer cells through JunB stabilization." (PMID 38038129, 2023).
tumor (15 papers, 2017 to 2026). "For example, we identified a high frequency of nonsynonymous mutations in ATXN3 in all primary tumour clones (clones 2, 3, 4, 6, 7, 9, and 10)." (PMID 34507604, 2021). "Although BNIP3- or NIX-induced mitophagy is associated with hypoxia, it is known that ataxin-3 can induce hypoxia in tumor cells; thus, hypoxia-mediated mitophagy may be relevant in SCA3/MJD." (PMID 39941093, 2025). "Indeed, ATXN3 expression is associated with tumor proliferation in gastric, lung, and testicular cancers." (PMID 32483272, 2020). "These in vivo results confirm the subtype-specific role of ATXN3, consistent with our in vitro findings, demonstrating that ATXN3 silencing enhances tumor growth in C33A and HeLa contexts but inhibits it in the SiHa model." (PMID 41507147, 2026). "To elucidate the functional role of ATXN3 in cervical carcinogenesis, we analyzed its expression in tumor tissues and matched adjacent non-tumor samples." (PMID 41507147, 2026). "ATXN3 knockdown significantly promoted tumor growth in C33A and HeLa models, while strongly suppressing it in SiHa-bearing mice." (PMID 41507147, 2026). "In BRCA, ATXN3 is significantly upregulated and promotes tumour metastasis and invasion by regulating KLF4." (PMID 40995818, 2025). "Nevertheless, given ATXN3's dual roles as both oncogenic and tumor-suppressive, prudence is essential in the development of ATXN3-targeting strategies for antitumor therapy." (PMID 38815863, 2024). "The Galectin-9-dependent tumor-suppressive functions of ATXN3 were further corroborated by a wound healing assay." (PMID 38815863, 2024). "Consistently, treatment of mice with ATXN3-null tumors with anti–PD-1 at the suboptimal dose of 50 μg nearly totally rejected the tumor, implying a synergistic effect of ATXN3 inhibition and anti–PD-1 therapy." (PMID 38038129, 2023). "To further support this, we observed that the WT and ATXN3-KO LLC1 tumor growth was comparable in immune-compromised nude mice." (PMID 38038129, 2023). "Third, ATXN3 promotes PD-L1 transcription in tumor cells through regulating multiple PD-L1 transcription–inducing pathways, including hypoxia and IFN-γ." (PMID 38038129, 2023). "Consistently, genetic ATXN3 suppression resulted in reduced PD-L1 expression and better B16 tumor rejection." (PMID 38038129, 2023). "Analysis of the PD-L1 expression on CD45– tumor cells confirmed that ATXN3 deletion resulted in a dramatic reduction in PD-L1 expression." (PMID 38038129, 2023). "Together with our discovery that ATXN3 drives tumor evasion of immunosurveillance through promoting PD-L1 transcription, targeting of this druggable enzyme will achieve both chemo- and immune-therapeutic efficacy in antitumor treatment." (PMID 38038129, 2023). "ATXN3-induced Pd-l1 transcription was promoted by tumor microenvironmental factors, including the inflammatory cytokine IFN-γ and hypoxia, through protection of their downstream transcription factors IRF1, STAT3, and HIF-2α." (PMID 38038129, 2023). "Surprisingly, when 25 μg anti–PD-1 antibody was used, we observed a more modest effect on suppressing WT tumor growth, but this dose still largely inhibited ATXN3-KO tumor growth." (PMID 38038129, 2023).
tumor (continued). "The current study identifies ATXN3 as a critical positive regulator for tumor invasion through promoting PD-L1 expression at the transcription level and provides a rationale for targeting this deubiquitinase in antitumor immune therapy." (PMID 38038129, 2023). "ATXN3 functions as a deubiquitinase for multiple transcription factors of PD-L1 in tumor cells in response to tumor microenvironmental factors." (PMID 38038129, 2023). "Several genes (including BCR, PCLO, ATXN3, PABPC3, and FADS6) were mutated in two or more PDX tumours." (PMID 33144587, 2020). "In contrast, TSPAN8 overexpression-enhanced tumor growth, but this enhancement was inhibited by the expression of ATXN3 shRNA." (PMID 31253779, 2019). "To further examine the role of TSPAN8- and ATXN3-regulated Hh signaling in tumor formation, we injected mice with MDA-MB-231 cells with or without depletion or overexpression of TSPAN8 in the presence or absence of expression of ATXN3 shRNA." (PMID 31253779, 2019). "Given that HPV oncoproteins like E7 are known to promote STAT5 activation, we hypothesize that in HPV16+ SCC, ATXN3 may facilitate tumor progression through the JAK3/STAT5 pathway." (PMID 41507147, 2026). "Intriguingly, the targeted removal of the ATXN3 gene led to a noteworthy decrease in the protein expression of Galectin-9, a carbohydrate-binding protein known for modulating immune response, inhibiting tumor cell growth, and inducing apoptosis." (PMID 38815863, 2024). "Additionally, our recent CRISPR screening identified ATXN3 as a positive regulator of the immune checkpoint receptor PD-L1, facilitating evasion of tumor immunosurveillance." (PMID 38815863, 2024). "Since ATXN3 suppression reduces tumor PD-L1 expression, we asked whether ATXN3 suppression in tumor cells improves anti–PD-1 therapeutic efficacy." (PMID 38038129, 2023). "Knockdown of ATXN3 significantly inhibited tumor proliferation, invasion and stem-like properties." (PMID 37349820, 2023). "Indeed, depletion of CD8+ T cells partially abolished the tumor growth inhibition caused by ATXN3 knockout, suggesting that CD8+ T cells mediate the elevated antitumor immunity by suppressing ATXN3." (PMID 38038129, 2023). "Under different genotoxic stress, JunB may act as an oncogene or tumor suppressor gene; our discoveries here imply that ATXN3 potentiates JunB oncogenic functions including PD-L1–mediated tumor evasion." (PMID 38038129, 2023). "In fact, we show here that suboptimal treatment with a lower dose of anti–PD-1 completely inhibited LLC1 syngeneic tumor growth owing to further elevation of the antitumoral immune response, providing a rationale for ATXN3 targeting in sensitizing antitumor immune therapy." (PMID 38038129, 2023). "This ATXN3-mediated PD-L1 upregulation enhances tumor evasion of antitumor immunity." (PMID 38038129, 2023). "Similarly, both the frequency and the PD-L1 expression levels of the myeloid cells from tumor-draining lymph nodes were comparable in WT and ATXN3-KO LLC1 tumors." (PMID 38038129, 2023). "Consistently, PD-L1 reconstitution partially reversed ATXN3 deletion–induced tumor suppression, indicating that additional unknown targets possibly exist for ATXN3 to achieve tumor immune evasive functions." (PMID 38038129, 2023). "Importantly, stable expression of PD-L1 on ATXN3-null LLC1 cells partially recovered the syngeneic tumor growth, indicating that ATXN3 potentiates tumor evasive function through, at least in part, PD-L1–mediated suppression of antitumor immunity." (PMID 38038129, 2023). "ATXN3 is a positive regulator of IFN-γ–induced PD-L1 transcription in tumor cells." (PMID 38038129, 2023). "Notably, a dramatic reduction in PD-L1 by ATXN3 deletion was detected in both LLC1 (more than 90% reduction) and B16 (more than 50% reduction) syngeneic tumors, indicating that ATXN3 plays a critical role in controlling PD-L1 expression in tumor microenvironment." (PMID 38038129, 2023).
tumor (continued). "Importantly, targeted deletion of ATXN3 dramatically reduced PD-L1 expression in all types of tumor cells tested, regardless of whether their proliferation was altered or not." (PMID 38038129, 2023). "The expression levels of ATXN3, METTL2A, PEX26 and UGGT1 in tumour cells were higher than those in normal mammary epithelial cells, and their expression in BRCA tissues was higher than that in normal adjacent tissues." (PMID 40995818, 2025). "The expression levels of ATXN3 | chr14:92526779, LOC100130744 | chr5:14716392, METTL2A | chr17:60528133, PEX26 | chr22:18572607 and UGGT1 | chr2:128949284 in tumour tissues were significantly higher than those in normal tissues (p < 0.05)." (PMID 40995818, 2025). "As a consequence, the production of tumor-infiltrating granzyme B and IFN-γ by CD8+ T cells in ATXN3-KO tumors was significantly increased." (PMID 38038129, 2023). "As expected, tumoral ATXN3 deletion resulted in a significant increase in CD4+ and CD8+ T cell tumor infiltration." (PMID 38038129, 2023). "The increases in expression of ATXN3 would be expected to repress the tumor suppressor PTEN, which negates several pathways involved in tumor growth." (PMID 32483272, 2020). "Indeed, upon LLC1 challenge, mice implanted with ATXN3-null LLC1 cells showed striking tumor rejection compared with those with WT LLC1 cells, with a dramatic reduction in both tumor volumes and weight." (PMID 38038129, 2023). "Notably, USP7, ATXN3, CSN5, and USP51 participate in tumor immunity within the GC microenvironment." (PMID 39605891, 2024). "Since ATXN3 promotes PD-L1 expression through STAT3 and HIF-2α, it will be interesting to test whether ATXN3 inhibition synergizes with STAT3- and HIF-2α–specific inhibitors in suppressing tumor growth, which could provide useful insights in translational studies." (PMID 38038129, 2023). "The elevated tumor rejection by ATXN3 suppression was largely diminished by CD8+ T cell depletion, confirming our initial conclusion that tumoral ATXN3 achieves its immune surveillance function in part through suppressing, either directly or indirectly, CD8+ T cell antitumor immunity." (PMID 38038129, 2023). "Importantly, this hypoxia-induced PD-L1 upregulation was largely, while not totally, diminished by ATXN3 targeted deletion, implying a possibility that ATXN3 enhances hypoxia-induced PD-L1 expression in tumor cells." (PMID 38038129, 2023). "The finding that stable PD-L1 expression could not fully rescue the ATXN3-null syngeneic tumor growth suggests that ATXN3 executes its tumorigenic functions in part through PD-L1–independent mechanisms." (PMID 38038129, 2023).
peripheral neuropathy (8 papers, 2011 to 2025). A disorder affecting the peripheral nervous system. "CAG expansions in ATXN3 lead to SCA3, which is characterized by peripheral neuropathy and ophthalmic change." (PMID 29186753, 2017).
neurological diseases (7 papers, 2012 to 2025). "According to the results of this study, ATXN3 is involved in the progression of many neurological diseases and mental health problems in a special way." (PMID 38233440, 2024). "We have recently reported that Usp14 is required for the stable expression of neurological disease-related proteins, such as tau and ataxin-3, in mouse embryonic fibroblasts." (PMID 23144711, 2012).
brain disorder (4 papers, 2019 to 2024). A disease affecting the brain or part of the brain. "As enhancer variations are being increasingly recognized as a cause of brain disorders, screening the enhancers of ATXN1, ATXN3, TBP and ITPR1 for variations other than CNVs and identifying and screening enhancers of other SCA genes might elucidate the genetic cause in undiagnosed patients." (PMID 39456985, 2024). "Together, the findings demonstrate that the possible sequence of events that leads to full-featured brain disease is composed of the changes at the level of many important proteins and phosphoproteins in the initial absence of mRNA changes dependent on mutant ataxin-3." (PMID 31201651, 2019).
autosomal dominant disease (3 papers, 2017 to 2020). Autosomal dominant form of disease. "Each subject has 2 ATXN3 alleles in autosomes, and if one of them is pathogenic, the subject is affected by SCA3 as it is an autosomal dominant disease." (PMID 33371889, 2020). "SCA3 is a rare autosomal dominant disease caused by abnormally extensive duplication of CAG repeats in the ATXN3 gene located on chromosome 14q." (PMID 28720120, 2017).
infection (3 papers, 2008 to 2023). The state of being infected such as from the introduction of a foreign agent such as serum, vaccine, antigenic substance or organism. "While bacterial invasion was unchanged, as evidenced by similar bacterial counts at 1 h post-infection, there was subsequently significantly greater bacterial survival in the ataxin-3 depleted cells that was maximal at 6 h." (PMID 31379806, 2019). "Misfolded mutant ataxin-3 proteins are detected within one week of infection and these ubiquitin-positive inclusions progressively accumulate in the nucleus of infected cells." (PMID 18841197, 2008). "Some of these, like ATG13 and ATXN3, are upregulated in VZV-infected cells, whereas, e.g., ATP2A2 is downregulated upon infection." (PMID 38025266, 2023).
ATXN3 also shares sentences with these, for which no sentence is quoted: cerebellar ataxia (21 papers); Alzheimer disease (18); spinocerebellar ataxia type 1 (11); Atrophy (9); Cerebellar atrophy (9); Cognitive impairment (9); depression (9); Tremor (8); frontotemporal dementia (7); Dystonia (6); multiple system atrophy (6); ataxia telangiectasia (5); Brain atrophy (5); proteinopathy (5); spinobulbar muscular atrophy (5); genetic disease (4); myotonic dystrophy type 1 (4); Niemann-Pick disease type C (4); Adult onset (3); episodic ataxia (3); movement disorder (3); multiple system atrophy of cerebellar type (3); neuropathy (3); Nystagmus (3); anaplastic thyroid carcinoma (2); autonomic dysfunction (2); Brainstem atrophy (2); cognitive decline (2); colorectal cancer (2); dementia (2).
A further 81 diseases each share a sentence with ATXN3 in 2 papers or fewer.